HSPB1 (heat shock protein family B (small) member 1)
Description:
Small heat shock protein which functions as a molecular chaperone probably maintaining denatured proteins in a folding-competent state. Plays a role in stress resistance and actin organization. Through its molecular chaperone activity may regulate numerous biological processes including the phosphorylation and the axonal transport of neurofilament proteins.
Synonyms: SRP27; HSP27; HSP28; Hs.76067; Hsp25; CMT2F; HEL-S-102; HMN2B; HMND3
Tractability: Small molecule: a high-quality ligand is known; it belongs to a druggable protein family. Antibody: its Gene Ontology location is reachable by antibodies, with medium confidence; the Human Protein Atlas places it where antibodies can reach. PROTAC: ubiquitination databases record sites on it; its protein half-life has been measured; a small molecule that binds it is known.
Target class: Other cytosolic protein
Gene: Protein-coding gene on chromosome 7 (76,302,673 to 76,305,813, forward strand). Ensembl gene ENSG00000106211.
Subcellular location: Cytoplasm; Nucleus; Cytoplasm, cytoskeleton, spindle
Subcellular location (Human Protein Atlas): Cytosol; Plasma membrane
Pathways (Reactome):
Cellular responses to stimuli: Attenuation phase; HSF1 activation; HSF1-dependent transactivation; Regulation of HSF1-mediated heat shock response
Signal Transduction: Extra-nuclear estrogen signaling; MAPK6/MAPK4 signaling; VEGFA-VEGFR2 Pathway
Metabolism of RNA: AUF1 (hnRNP D0) binds and destabilizes mRNA
Gene Ontology:
Molecular function: identical protein binding; protein binding; protein folding chaperone; protein homodimerization activity; protein kinase binding; RNA binding; RNA polymerase II-specific DNA-binding transcription factor binding; protein kinase C binding; protein kinase C inhibitor activity; ubiquitin binding
Biological process: anterograde axonal protein transport; cellular response to vascular endothelial growth factor stimulus; intestinal epithelial structure maintenance; intracellular signal transduction; negative regulation of oxidative stress-induced intrinsic apoptotic signaling pathway; platelet aggregation; positive regulation of angiogenesis; positive regulation of blood vessel endothelial cell migration; positive regulation of endothelial cell chemotaxis; protein folding; regulation of protein phosphorylation; response to virus; vascular endothelial growth factor receptor signaling pathway; negative regulation of apoptotic process; negative regulation of protein kinase C signaling; positive regulation of interleukin-1 beta production; positive regulation of tumor necrosis factor production; protein refolding; regulation of autophagy; regulation of canonical NF-kappaB signal transduction; regulation of translational initiation; response to heat; response to unfolded protein; protein stabilization
Cellular component: cytoplasm; cytosol; extracellular exosome; extracellular region; focal adhesion; nucleus; plasma membrane; cytoskeleton; proteasome complex; axon cytoplasm; contractile muscle fiber; cornified envelope; spindle; Z disc
Genetic constraint (gnomAD): Loss-of-function variants: 20 observed, 14.09 expected, observed/expected ratio (o/e) 1.42, 90% interval 0.99 to 1.89. The synonymous counts are far from expectation, so gnomAD's model fits this gene poorly and the ratio says little. Missense variants: 348 observed, 256.08 expected, observed/expected ratio (o/e) 1.36, 90% interval 1.24 to 1.49. Synonymous variants: 165 observed, 115.82 expected, observed/expected ratio (o/e) 1.42, 90% interval 1.25 to 1.62.
Gene-disease validity (ClinGen):
ClinGen rates the evidence that HSPB1 causes each of these diseases.
Charcot-Marie-Tooth disease axonal type 2F (autosomal dominant): Definitive.
Homologues: Orthologues: chimpanzee HSPB1 (100% identical), macaque HSPB1 (100% identical), rabbit HSPB1 (91% identical), dog HSPB1 (89% identical), pig HSPB1 (89% identical), guinea pig HSPB1 (86% identical), mouse Hspb1 (84% identical), rat Hspb1 (83% identical), tropical clawed frog hspb1 (69% identical), zebrafish hspb1 (59% identical), Drosophila melanogaster CG14207 (25% identical), Caenorhabditis elegans hsp-25 (24% identical), and 8 more. Paralogues in human: CRYAB (38% identical), HSPB8 (35% identical), CRYAA (34% identical), HSPB2 (32% identical), HSPB6 (29% identical), HSPB3 (22% identical), HSPB7 (21% identical), HSPB9 (14% identical).
Diseases named in the same sentence as HSPB1 in open-access papers:
HSPB1 is named in the same sentence as 277 diseases in open-access papers, as found by Europe PMC text mining. Sharing a sentence is not in itself a finding about the gene and the disease. The quoted sentences say what the papers report.
breast cancer (44 papers, 2007 to 2026). A primary or metastatic malignant neoplasm involving the breast. "Based on TCGA and GEO databases, HSPB1 expression was upregulated in breast cancer tissues and associated with poor prognosis of breast cancer patients, which was considered an independent prognostic factor for breast cancer." (PMID 37454220, 2023). "Collectively, these findings indicated that HSPB1 expression was increased in breast cancer tissues and associated with poor prognosis of breast cancer patients." (PMID 37454220, 2023). "The results indicated that high expression of HSPB1 was significantly associated with distant metastasis in breast cancer (p < 0.001), indicating a potential role of HSPB1 in breast cancer progression." (PMID 37454220, 2023). "To better understand the relevance and underlying mechanisms of HSPB1 expression in breast cancer, we summarized the distribution of clinicopathological information of patients in HSPB1 high expression group and HSPB1 low expression group." (PMID 37268925, 2023). "The potential relevance of HSPB1 and its underlying mechanisms in the development of breast cancer have yet to be elucidated." (PMID 37268925, 2023). "In the current study, we identified that high expression of HSPB1 was associated with poor prognosis of breast cancer patients." (PMID 37454220, 2023). "IL6 has also been reported to induce macrophage polarization to the M2-phenotype in various cancers, however, the association between HSPB1 and M2 polarization in breast cancer needed to be further elucidated." (PMID 37454220, 2023). "The expression of HspB1, HspB2, and HspB5 is reported to be associated with resistance to apoptosis in human breast cancer cells and oral verrucous carcinoma." (PMID 32927696, 2020). "Current research highlights the Hspb1 based screening of eight cat populations of the world to investigate the association of newly found locus within cat mammary tumors." (PMID 28224005, 2016). "High levels of HSPB1 were associated with significantly increased survival in luminal A breast cancer patients." (PMID 26847234, 2016). "HSPB1 levels were found to be lower in caveolin-1-deficient breast cancer cells, and the treatment of keratinocytes with agents such as filipin or methyl-β-cyclodextrin that disrupt lipid raft-caveolae suppressed sulfur mustard-induced HSPB1 mRNA and protein expression." (PMID 35806322, 2022). "Additionally, phosphorylated HspB1 is also reported to be associated with portal vein invasion in hepatocellular carcinoma and lymph node metastasis in breast cancer." (PMID 32927696, 2020). "The angiogenic properties of secreted HSPB1 were related to an ability to cause local differentiation of monocytes into tumor associated macrophages that lose tumoricidal activity but elicit angiogenic responses in breast cancer." (PMID 28468249, 2017). "The current research endeavour enlighten us that 4 bp deletion in intron 2 at splice site of Hspb1 gene might be associated with mammary tumor in Felis catus." (PMID 28224005, 2016). "Moreover, high expression of HSPB1 was associated with a worse prognosis in breast cancer patients." (PMID 37454220, 2023). "HSPB1 regulates estrogen receptor-positive (ER+) breast cancer cell proliferation in a SLC7A5-dependent manner." (PMID 42208896, 2026).
breast cancer (continued). "For instance, inhibiting crVDAC3 can induce ferroptosis in breast cancer cells by reducing HSPB1 expression, thereby mediating resistance to deruxtecan in HER2-low breast cancer." (PMID 40009842, 2025). "For instance, HSPB1 inhibits ferroptosis in breast cancer cells by regulating the NF-kB pathway, thereby contributing to chemotherapy resistance." (PMID 39834939, 2024). "For example, by reducing the expression of HSPB1, crVDAC3 induces ferroptosis in breast cancer cells, thereby mediating the resistance of HER2-low breast cancer to trastuzumab-deruxtecan." (PMID 39871946, 2024). "Previous findings suggest that heat shock protein beta-1 (HSPB1) contributes to doxorubicin resistance by shielding breast cancer cells from drug-induced ferroptosis." (PMID 39135991, 2024). "These discoveries imply that HSPB1 fosters chemoresistance by preventing ferroptosis and influencing the NF-κB signaling pathway in breast cancer cells." (PMID 39135991, 2024). "HSPB1 inhibits ferroptosis in breast cancer cells and regulates the NF-κB signaling pathway to promote chemoresistance." (PMID 39664391, 2024). "Our study evaluated the expression levels, clinicopathological associations, clinical significance, and influence on metastasis of HSPB1 in breast cancer." (PMID 37268925, 2023). "As HSPB1 expression levels are intimately related to breast cancer progression, Kaplan–Meier survival curves were used to compare the expression levels of HSPB1 with prognosis." (PMID 37268925, 2023). "The results indicated that HSPB1 overexpression decreased erastin-induced growth inhibition and ROS production in breast cancer cells, and Fer-1 treatment showed a synergistic effect with HSPB1 overexpression." (PMID 37454220, 2023). "We first analyzed the mRNA expression in several public breast cancer datasets, and hierarchical clustering analysis revealed that the expression of HSPB1 was upregulated in breast cancer tissues compared to normal tissues based on TCGA and GEO databases." (PMID 37454220, 2023). "Our results indicated that erastin (an inducer of ferroptosis) treatment led to increased mRNA and protein levels of HSPB1 in a dose-dependent manner in breast cancer cells, which is consistent with the observations in other cancer cells." (PMID 37454220, 2023). "While the relationship between HSPB1 and tumorigenesis has been demonstrated, limited evidence has illustrated the clinical significance and function of HSPB1 in breast cancer." (PMID 37268925, 2023). "Elevated mRNA and protein expression levels of HSPB1 were identified in doxorubicin-resistant breast cancer cells (MDA-MB-231/DOX, 231/DOX) compared with parental cells (MDA-MB-231, 231), indicating its promoting role in doxorubicin resistance." (PMID 37454220, 2023). "Our observations provide a foundational rationale that targeting HSPB1 and combinational induction of ferroptosis with anticancer drugs would be a potential therapeutic strategy to overcome chemoresistance in breast cancer." (PMID 37454220, 2023). "Consistently, breast cancer cells transfected with si-HSPB1 showed attenuated resistance to doxorubicin compared to cells transfected with si-NC." (PMID 37454220, 2023). "In this study, a transient knockdown of HSPB1 inhibited cell proliferation and migration/invasion activity and promoted apoptosis of breast cancer cells." (PMID 37268925, 2023). "This study advances our current understanding of the role of HSPB1 as a prognostic marker for breast cancer treatment." (PMID 37268925, 2023). "Significantly, the IC50 value of doxorubicin was significantly higher in HSPB1 overexpressing breast cancer cells compared to that in control cells." (PMID 37454220, 2023). "We investigated the expression of HSPB1 in patients with breast cancer using The Cancer Genome Atlas and immunohistochemistry." (PMID 37268925, 2023).
breast cancer (continued). "Through bioinformatic analysis, we found that HSPB1 expression was upregulated in most cancers, such as breast cancer, kidney cancer, liver cancer and glioma." (PMID 37241117, 2023). "In the study, we identified upregulated HSPB1 expression in breast cancer tissues based on the results obtained from several public datasets, which was further confirmed using tissues from our cohort." (PMID 37454220, 2023). "In this study, SK-BR-3 and MDA-MB-231 breast cancer cells with the high protein expression of HSPB1 were selected as research subjects." (PMID 37268925, 2023). "The results showed that the expression of HSPB1 in the tumour tissues of breast cancer, kidney cancer, liver cancer and glioma was higher than in the normal tissues." (PMID 37241117, 2023). "Overall, high HSPB1 expression predicted poor clinical outcomes, meaning that it holds potential as a novel prognostic biomarker for breast cancer." (PMID 37268925, 2023). "HSPB1 overexpression inhibited while HSPB1 knockdown increased erastin-induced intracellular concentrations of lipid ROS in breast cancer cells, which is one of the significant signatures of ferroptosis." (PMID 37454220, 2023). "Consistently, the IHC staining also revealed that the protein expression of HSPB1 was upregulated in breast cancer tissues compared to normal tissues according to Qilu cohort and TCGA dataset." (PMID 37454220, 2023). "Altogether, these results strengthened the effect of HSPB1 on doxorubicin resistance through regulating ferroptotic cell death in breast cancer cells." (PMID 37454220, 2023). "Several studies have confirmed that HSPB1 methylation is a biomarker in prostate cancer, breast cancer, colorectal cancer and malignant melanoma." (PMID 37241117, 2023). "We further detected the expression of HSPB1 in human breast cancer tissues and adjacent normal tissues in a cohort of patients from Qilu Hospital, and upregulated mRNA expression of HSPB1 was also detected in breast cancer tissues." (PMID 37454220, 2023). "Based on the differential analysis of data from TCGA and GEO databases, we identified that the expression of Heat shock protein beta-1 (HSPB1), a member of the human small heat shock proteins (HSPBs), was significantly upregulated in breast cancer tissues." (PMID 37454220, 2023). "Significantly, age, LN metastasis, distant metastasis, and HSPB1 expression were considered independent prognostic indicators for disease-free survival of breast cancer." (PMID 37454220, 2023). "The MTT and colony formation assays indicated that HSPB1 overexpression promoted breast cancer cell proliferation." (PMID 37454220, 2023). "HSPB1 knockdown inhibited the proliferation, migration, invasion, and apoptosis of breast cancer cells." (PMID 37268925, 2023). "A higher expression of HSPB1 in breast cancer tissue when comparing the immunohistochemical analysis in of 18 cancerous and non-cancerous sample pairs." (PMID 37268925, 2023). "In this study, we used a systematic and comprehensive approach to assess the relationship between HSPB1 expression and clinicopathological characteristics in patients with breast cancer." (PMID 37268925, 2023). "We found that age, >3 LN metastasis, and HSPB1 expression were independent prognostic indicators for the overall survival of breast cancer." (PMID 37454220, 2023). "We further revealed the relevance of HSPB1 in the regulation of chemoresistance of breast cancer for the first time, which was mediated by chemotherapeutics-induced ferroptosis." (PMID 37454220, 2023). "According to our findings, the expression of HSPB1 was considerably upregulated in breast cancer tissues, which is consistent with a previous report." (PMID 37268925, 2023). "We further evaluated the function of HSPB1 in breast cancer in vivo using a nude mouse xenograft model." (PMID 37454220, 2023).